SCD (stearoyl-CoA desaturase)
Diseases named in the same sentence as SCD in open-access papers (continued):
Sharing a sentence is not in itself a finding about the gene and the disease.
breast tumors (9 papers, 2015 to 2024). "Moreover, the pattern of SCD expression observed in primary breast tumour compared to circulating and metastatic cells resemble that observed in low- and high-density cultures, respectively." (PMID 39433871, 2024). "MiR-600 acts as a regulator of WNT signalling through SCD-1 to regulate breast tumour genesis." (PMID 33319811, 2020). "As yet, little is known about the possible pathophysiological role of this other human SCD isoform in cancer and our findings encourage exploring its involvement in breast tumor progression with particular reference to the elucidation of the molecular mechanisms of tumor cell growth and survival." (PMID 29849946, 2018). "Although we have not detected differences by histological type, it has been described that SCD-1 expression is greater in HR+ and HER2+ BC subtypes than in TN breast tumors." (PMID 33066483, 2020).
colitis (9 papers, 2012 to 2025). Inflammation of the colon. "We further demonstrate that local inhibition of SCD alleviates colitis severity and modulates inflammatory responses in vivo." (PMID 41515900, 2025). "The integrated multi-omics characterization of colitis revealed decreased brain chenodeoxycholic acid (CDCA) levels as well as reduced stearoyl-CoA desaturase (Scd1) gene and protein expression." (PMID 40076732, 2025). "Functional validation confirmed that inhibiting SCD ameliorated disease severity and suppressed pro-inflammatory signaling in experimental colitis, highlighting its therapeutic potential." (PMID 41515900, 2025). "Second, although SCD inhibition alleviated colitis, its specific effects on ferroptosis markers (e.g., GSH, MDA, lipid ROS) were not quantitatively measured." (PMID 41515900, 2025). "In the DSS-induced colitis model, local inhibition of SCD significantly ameliorated the severity of colitis." (PMID 41515900, 2025). "A consistent pattern was observed across both models: the protein level of GPX4, a master inhibitor of ferroptosis, was significantly restored in the SCD inhibitor-treated groups compared to the colitis control groups." (PMID 41515900, 2025). "We therefore employed the TNBS-induced colitis model to further validate the therapeutic potential of SCD inhibition, as this model better replicates the transmural inflammation characteristic of CD." (PMID 41515900, 2025). "Importantly, localized inhibition of SCD alleviated disease severity in experimental colitis." (PMID 41515900, 2025). "To functionally validate the role of SCD in intestinal inflammation and its potential interaction with ferroptosis, we employed both dextran sulfate sodium (DSS)-induced and 2,4,6-trinitrobenzenesulfonic acid (TNBS)-induced murine colitis models." (PMID 41515900, 2025).
cervical carcinoma (8 papers, 2017 to 2026). A carcinoma arising from either the exocervical squamous epithelium or the endocervical glandular epithelium. "CA9, TFRC and SCD are all risk factors for cervical cancer, so we predicted candidate drugs for these genes, among which 2-(4-morpholinyl)-8-phenyl-4H-1-benzopyran-4-one and oxygen could regulate all three of these risk factors." (PMID 36313765, 2022). "Together, the results suggested that CA9, TFRC, and SCD were risk factors for cervical cancer." (PMID 36313765, 2022). "SCD and TFRC were expressed in both normal cervical and cervical cancer tissues, while CA9 was expressed in only cervical cancer tissues." (PMID 36313765, 2022). "Here we found that it also had the potential to treat cervical cancer, in a mechanism involving CA9, TFRC, and SCD." (PMID 36313765, 2022).
heart failure (8 papers, 2011 to 2025). Inability of the heart to pump blood at an adequate rate to meet tissue metabolic requirements. "In agreement with a role of SCD in human heart failure pathogenesis, increased circulating markers of enhanced stearoyl-CoA desaturase activity were associated with an elevated risk of heart failure development and all-cause mortality in human subjects." (PMID 34576047, 2021). "Human plasma SCD activity is also associated with the risk of heart failure." (PMID 37233656, 2023). "In agreement with a negative impact on heart function, increased plasma contents of unsaturated palmitoleic acid as a marker of increased systemic stearoyl-CoA desaturase activity were found to be associated with an elevated risk of heart failure in human subjects." (PMID 34576047, 2021). "With this strategy and in view of our study, the development of systemic SCD inhibitors for patient use appears as a promising strategy to improve heart failure treatment options." (PMID 34576047, 2021). "These symptoms of heart failure were accompanied by up-regulation of heart-failure-promoting lipid genes, Fasn and Scd1, and heart failure markers, Retn and Adipoq, in Tg-SCD hearts." (PMID 34576047, 2021). "Thus, SCD-induced symptoms of heart failure are accompanied by up-regulation of the murine Scd1 transcript as another heart-failure-related gene of the lipid metabolic process." (PMID 34576047, 2021). "Because the pathophysiological role of Scd1/SCD in heart failure is not clear, we investigated the impact of cardiac SCD upregulation through the generation of C57BL/6-Tg(MHCSCD)Sjaa mice with myocardium-specific expression of SCD." (PMID 34576047, 2021).
osteosarcoma (8 papers, 2015 to 2025). A usually aggressive malignant bone-forming mesenchymal neoplasm, predominantly affecting adolescents and young adults. "Another study in the same month verified that inhibiting stearoyl-CoA desaturase can impair the proliferation and invasion of osteosarcoma and become a therapeutic target for new drugs." (PMID 39445018, 2024). "The present study surprisingly found an induction of SCD-1 levels in human osteosarcoma cells under high shear force stimulation through Smad1/5-PPARδ signaling, which consequently affects the osteosarcoma survival (differentiation and cell death)." (PMID 32630668, 2020). "Smad1 and Smad5 gene knockdown significantly inhibited SCD-1 protein expression of 20 dynes/cm2 shear force induction in MG63 osteosarcoma cells." (PMID 32630668, 2020). "The present study finds a possible auto-protective role of SCD-1 upregulation in high shear force-damaged human MG63 osteosarcoma cells." (PMID 32630668, 2020). "In the present study, we further investigated the possible role of SCD-1 in shear force effect on human MG63 osteosarcoma cells." (PMID 32630668, 2020). "It was shown that only PPARδ gene knockdown inhibits 20 dynes/cm2 shear force-induced SCD-1 protein expression in human MG63 osteosarcoma cells." (PMID 32630668, 2020). "The present study further found a surprising upregulation of SCD-1 level in human MG63 osteosarcoma cells in response to this destructed high shear force." (PMID 32630668, 2020). "Combined with these studies, we suggested that transcription regulation of SCD-1 is also in a context-dependent manner and PPARδ could be another transcription mediator in osteosarcoma cells under high shear force stimulation." (PMID 32630668, 2020). "This suggestion could be supported by a perspective that differentiation promotion might be one novel anti-osteosarcoma therapeutic strategy and by the increasing data finding a positive correlation between SCD-1 activity inhibition and cancer cell death." (PMID 32630668, 2020). "Although our results could not completely provide the precise explanation yet, we reasonably suggested that SCD-1 upregulation in high shear force-damaged MG63 osteosarcoma cells might be an auto-protective mechanism." (PMID 32630668, 2020). "However, the more detailed and precise role of SCD-1 upregulation should be further investigated in various osteosarcoma cells and in vivo experimental designs." (PMID 32630668, 2020). "Next, we determined whether SCD-1 upregulation in MG63 osteosarcoma cells under 20 dynes/cm2 shear force stimulation also controls the cell death." (PMID 32630668, 2020). "Thus, combined with these previous findings, the present study defined 2 and 20 dynes/cm2 shear intensity as low and high shear force respectively, to investigate the shear effect on SCD-1 regulation in osteosarcoma cells and subsequent cell fate control." (PMID 32630668, 2020). "Moreover, gene knockdown of PPARδ and SCD-1 in human MG63 osteosarcoma cells attenuated the differentiation inhibition and resulted in much more cell death of high shear force initiation." (PMID 32630668, 2020). "Moreover, while the SCD-1 gene was knocked down in human MG63 osteosarcoma cells, the differentiation inhibition and cell death of high shear force stimulation were significantly attenuated and more promoted, respectively." (PMID 32630668, 2020). "The proposed study was carried out on these bases and further found the correlation between lipid metabolism and shear force regulation of cancer cells, which elucidated a possible auto-protective role of SCD-1 upregulation in high shear force (20 dynes/cm2)-stimulated cell death of osteosarcoma." (PMID 32630668, 2020). "Our findings elucidate an interesting role of SCD-1 upregulation in human osteosarcoma while the cells are exposed to high shear force and suggest that this SCD-1 upregulation might contribute a complicated regulatory mechanism to affect the cancer cell survival." (PMID 32630668, 2020).
osteosarcoma (continued). "Thus, we examined whether Smad1/5 signaling also affects 20 dynes/cm2 shear force-induced SCD-1 expression in human MG63 osteosarcoma cells." (PMID 32630668, 2020). "Moreover, this SCD-1 induction could contribute to cell fate regulation in human MG63 osteosarcoma cells." (PMID 32630668, 2020). "Moreover, interesting results showed that cells transfected with PPARδ- or SCD-1-specific siRNA to knockdown the corresponding gene expression enhance the cell death effect of 20 dynes/cm2 shear force stimulation more in human MG63 osteosarcoma cells." (PMID 32630668, 2020). "It was shown that 20 dynes/cm2 shear force significantly induces SCD-1 protein and mRNA expressions in human MG63 osteosarcoma cells after 8 and 24 h of treatment, which is approximately 3~4 times that of the untreated controls." (PMID 32630668, 2020). "Immunoblotting of cell extracts demonstrated that FASN and SCD-1 levels were very low or non-detectable in human MSCs compared with the osteosarcoma cell lines." (PMID 33289496, 2021). "Interestingly, gene knockdown of PPARδ or SCD-1 seemed to partially increases the endogenous Runx2 and OCN mRNA expressions in MG63 osteosarcoma cells." (PMID 32630668, 2020). "A SCD-1 upregulation in human MG63 osteosarcoma cells under 20, but not 2, dynes/cm2 shear force stimulation was shown, and this induction was regulated by Smad1/5 and peroxisome proliferator-activated receptor δ (PPARδ) signaling." (PMID 32630668, 2020). "We found that 20, but not 2, dynes/cm2 shear force surprisingly increases the SCD-1 levels in human MG63 osteosarcoma cells through the activation of Smad1/5 signaling and PPARδ transcriptional factor." (PMID 32630668, 2020). "Across all Ewing and osteosarcoma cell lines eleven genes were found to be either significantly (P < 0.05, Bonferroni correction) repressed (KIF20A, IDH1, SCD, GPSM2, EIF2AK4, HIBCH) or induced (STK19, DNAJC24, MTG2, FAM175B, CYB5D1) following non DNA-damaging XI-006 treatment (0.5 μM)." (PMID 26095524, 2015). "Moreover, cells transfected with PPARδ- or SCD-1-specific siRNA to knockdown the corresponding gene expression significantly recovered the inhibitory effect of 20 dynes/cm2 shear force on Runx2 and OCN mRNA expressions in human MG63 osteosarcoma cells." (PMID 32630668, 2020). "However, in the present results, only PPARδ and PPARγ, but not PPARα, expressions were increased in MG63 osteosarcoma cells in response to high shear force stimulation, and further results found that only PPARδ is involved in mediating SCD-1 upregulation of high shear force stimulation." (PMID 32630668, 2020).
ovarian tumor (8 papers, 2017 to 2025). "Notably, DUSP9 significantly upregulated SCD—a key lipogenic enzyme and known metabolic vulnerability in multiple cancers, including breast and ovarian tumors." (PMID 41383134, 2025). "Thus, being considered as a target for chemotherapy, SCD therapeutic inhibition affects tumor growth in several xenograft models (prostate, kidney, gastric or ovarian tumor." (PMID 30913248, 2019). "For instance, fatty acid synthase (FASN) and stearoyl-CoA desaturase (SCD1) are elevated in high-grade, metastatic ovarian tumors and lead to elevated levels of unsaturated fatty acids." (PMID 35634242, 2022).
renal carcinoma (8 papers, 2015 to 2025). A carcinoma arising from the epithelium of the renal parenchyma or the renal pelvis. "In patient-derived tissues, SCD expression was upregulated in many urological cancers, including PRAD and renal cancer, compared to adjacent normal tissues." (PMID 39351232, 2024).
asthma (7 papers, 2021 to 2025). "Interestingly, reduced levels of SCD and altered fatty acid metabolism have been reported in asthma." (PMID 36264868, 2022).
liver disease (7 papers, 2013 to 2026). "Further investigations are needed to confirm in humans the results obtained in mice with MASLD-related liver disease by aramchol, a partial inhibitor of hepatic stearoyl-CoA desaturase (SCD1)." (PMID 41011192, 2025).
schizophrenia (7 papers, 2007 to 2025). A major psychotic disorder characterized by abnormalities in the perception or expression of reality. "Since stearoyl-CoA desaturase, the rate-limiting enzyme of OA, has been found to cause neurotoxicity by producing MUFAs and impairing microglia and macrophages, the possibility exists that this mechanism affects cognitive function in patients with schizophrenia." (PMID 38716119, 2024). "Interestingly, we identified genes associated with fatty acid metabolism amongst VMPs with concordant changes in blood and brain, including HSD17B4, CYP4V2, FADS2, and SCD, indicating altered DNA methylation variance may impact fatty acid metabolism in these tissues in schizophrenia." (PMID 39271751, 2025).
synucleinopathies (7 papers, 2020 to 2025). "We previously identified stearoyl-CoA desaturase (SCD) as a potential therapeutic target for synucleinopathies." (PMID 35445353, 2022). "Stearoyl-CoA desaturase (SCD) was identified as a potential target for synucleinopathies through unbiased phenotypic screening and target deconvolution in yeast models." (PMID 35060064, 2022). "This link between lipid biology and αSyn is supported by recent evidence from cell-based screens of αSyn toxicity that identified stearoyl-CoA desaturase (SCD) as a potential target for treatment of synucleinopathies." (PMID 35445353, 2022). "Based on emerging links between αSyn pathology and lipid biology, which includes the demonstrated evidence for SCD inhibition in mitigating αSyn pathologies, a medicinal chemistry campaign was initiated to identify brain-penetrant SCD inhibitors as therapeutics for synucleinopathies." (PMID 35445353, 2022). "SCD inhibition has emerged as a potential new treatment for synucleinopathies in several studies." (PMID 34254125, 2021). "Our data demonstrating broad protection against diverse αSyn-dependent phenotypes by SCD inhibition, along with the established links among αSyn, lipids, and PD, support the continued development of YTX-7739 as a therapeutic agent for synucleinopathies." (PMID 35445353, 2022). "Together, these data provide further validation of SCD as a PD therapeutic target and YTX-7739 as a clinical candidate for treating human α-synucleinopathies." (PMID 35445353, 2022).
triple-negative breast carcinoma (7 papers, 2016 to 2025). An invasive breast carcinoma which is negative for expression of estrogen receptor (ER), progesterone receptor (PR), and human epidermal growth factor receptor 2 (HER2). "In keeping with this finding, three out of the four triple negative breast cancer cell lines used in this study showed high sensitivity towards SCD depletion." (PMID 27042297, 2016). "Here we demonstrate that in triple-negative breast cancer (TNBC) cells, the seeding density positively regulates the expression of genes involved in fatty acid synthesis and desaturation (i.e., SCD)." (PMID 39433871, 2024).
alopecia (6 papers, 2011 to 2024). Hair loss usually from the scalp. "Despite this, topical and intraperitoneally injected SCD inhibitors produce unwanted side effects, such as dry eyes, partial eye closure, dry skin, and alopecia." (PMID 33207603, 2020). "Despite significant downregulation of SCD with consequent alterations in the relative abundance of fatty acids in MBTPS2-OI fibroblasts, the MBTPS2-OI patients in our study did not present with alopecia or photophobia." (PMID 34093655, 2021).
Glucose intolerance (6 papers, 2012 to 2024). Glucose intolerance (GI) can be defined as dysglycemia that comprises both prediabetes and diabetes. "Levels of saturated fatty acids, the desaturases SCD and D9D, and corresponding MUFAs, correlated with margarine intake and were generally associated with decreased metabolic health and glucose intolerance." (PMID 30400149, 2018).
Hypertension (6 papers, 2021 to 2026). The presence of chronic increased pressure in the systemic arterial system. "The activity of SCD is very high in patients with cardiovascular disease, hypertension, and diabetes; moreover, the ratios of FFA 16:1/FFA 16:0 and FFA 18:1/FFA 18:0 levels are considered as reference values to estimate the activity of SCD36." (PMID 36180468, 2022).
leukemia (6 papers, 2016 to 2025). A malignant (clonal) hematologic disorder, involving hematopoietic stem cells and characterized by the presence of primitive or atypical myeloid or lymphoid cells in the bone marrow and the blood. "Inhibiting the activity of SCD induces leukemia cell apoptosis and may be a novel way to eradicate leukemia stem cells." (PMID 36338749, 2022). "The mice injected with SCD overexpressing cells showed enhanced CNS infiltration relative to control animals pointing to the role of SCD-mediated lipid metabolism in facilitating leukemia adaptation to the CNS niche." (PMID 34957100, 2021).
neuroblastoma (6 papers, 2021 to 2026). Neuroblastoma (NB) is the most common solid, extracranial childhood tumor. "Similar to FASN, SCD has been strongly implicated in the development and progression of neoplastic disease including a neuroblastoma that is also vulnerable to treatment with polyamine pathway inhibitors." (PMID 39337514, 2024). "Notably, SCD inhibition by CAY or MF caused an increase in SCD1 mRNA and protein levels in our neuroblastoma model and our primary neuron cultures." (PMID 34301719, 2021). "Despite the issues with high inhibitor concentrations, we found similar results in the suppression of αSyn 3K accumulation formation and cytotoxicity with SCD inhibition in our neuroblastoma model." (PMID 34301719, 2021). "In a similar neuroblastoma model it was found that αSyn 3K protein levels were unchanged up to 10 μm SCD inhibitor concentrations, although the CAY inhibitor showed a trend of protein lowering." (PMID 34301719, 2021). "Furthermore, SCD inhibition fully restored cell growth in neuroblastoma cells with doxycycline-inducible α-syn-3 K::YFP expression, while not reducing cell growth in the absence of doxycycline." (PMID 39563397, 2024). "Indeed, we and others have demonstrated that loss/inhibition of the OA-generating enzyme stearoyl-CoA desaturase (SCD) rescues αS-related toxicity in yeast, Caenorhaditis elegans, primary rodent neurons and neuroblastoma cells." (PMID 34254125, 2021). "We also confirm that SCD inhibitors reduce formation of αSyn accumulations, while OLA increases these accumulations in an αSyn 3K neuroblastoma model." (PMID 34301719, 2021).